APOE (apolipoprotein E)
Diseases named in the same sentence as APOE in open-access papers (continued):
Sharing a sentence is not in itself a finding about the gene and the disease.
diabetes (continued). "Using different statistical approaches, in this study, we have confirmed that the single nucleotide polymorphism rs3737787 is related to triglyceride and apolipoprotein E levels in type 2 diabetes mellitus families." (PMID 23675152, 2009). "Diabetes in apolipoprotein-E (ApoE)-deficient mice isassociated with a significant accumulation of extracellular matrix proteins andincreased immunostaining for collagen IV in the glomerular compartments." (PMID 19283081, 2008). "Development of sporadic late-onset AD is associated to age, vascular factors, inflammation and diabetes as well as established susceptibility genes such as apolipoprotein E (APOE) and the most recently discovered SORL1." (PMID 19415125, 2007). "Furthermore, combination with APOE ε4 (+), diabetes mellitus or hypertension increased the risk of MCI/AD in IHD." (PMID 40015755, 2025). "Vascular calcifications were independently associated with increased all-cause mortality in RA patients.IL-4 and anti-citrullinated ApoE levels were significantly elevated in patients with vascular calcifications.Prednisone use and diabetes were positively associated with vascular calcifications." (PMID 41179568, 2025). "In the current study, firstly, we investigated the association between Apolipoprotein E polymorphisms and the risk of type 2 diabetes mellitus in obese Egyptian populations, and the results revealed that the Ɛ3/Ɛ4 genotype was the most frequent among all groups studied." (PMID 39138505, 2024). "In effect, APOE polymorphisms may be involved in the regulation of overall metabolic abnormalities (e.g. impaired glucose metabolism, dyslipidemia, and type 2 diabetes mellitus)." (PMID 39561140, 2024). "However, there are different risk factors for sporadic AD that include age, gender, apolipoprotein E (apoE) genotype and metabolic disorders such as diabetes, hypertension, and hypercholesterolemia, among others." (PMID 36769268, 2023). "In addition to atherosclerotic disease, APOE polymorphisms have been studied as factors associated with various pathological conditions such as neurodegenerative pathologies, diabetes, kidney disease, worse cognitive ability, stroke and cancer." (PMID 37629219, 2023). "The common risk factors for the development of AD are increased age, family history, degeneration or vascular dysfunction, obesity, hypotension or hypertension, diabetes, hyperlipidemia, and the existence of epsilon 4 allele of the apolipoprotein E gene (ApoE4)." (PMID 36835994, 2023). "However, APOE ε4 carriers and non-ε4 carriers had similar vascular risk factors (hypertension 66.67% vs. 70.83%, p = 0.13; diabetes 27.49% vs. 30.31%, p = 0.30) as well as stroke severity (NIHSS, p = 0.23)." (PMID 36640294, 2023). "Total caloric intake, age, gender, education, civil status, physical activity, smoking,BMI, vitamin/mineral supplement intake, vascular disorders, diabetes, cancer, depression, presence of APOE ε4 allele, and dietary components other than those included in each dietary index." (PMID 37513622, 2023). "It is possible that APOE polymorphism collaborates with other comorbidity factors, such as obesity, chronic infection, hyperlipidemia, hypertension, and neurodegenerative disorders to exacerbate diabetes progression." (PMID 36077289, 2022). "Furthermore, dyslipidemia related to apolipoprotein E (APOE) e4 alleles, caused by diabetes, leads to lower cognitive performance, lower attention and lower motor function." (PMID 35328405, 2022). "Similar to the inconsistencies reported in the literature regarding the relationship between APOE polymorphism and obesity in humans, whether APOE polymorphism has direct influence on insulin resistance and diabetes is also controversial." (PMID 36077289, 2022). "Second, APOE gene polymorphisms are associated with the development of diabetes, but the underlying mechanism is currently unknown." (PMID 36426228, 2022).
diabetes (continued). "Moreover, diabetes has been classified as a risk factor for AD, especially when associated with the APOE ε4 genotype." (PMID 34956307, 2021). "We repeated the models for VaD, with rs9923231 as a predictor and with the simultaneous addition of concentration of triglycerides, APOE variant, diagnoses of hypertension (n = 84,694), hypercholesterolemia (n = 40,363), and diabetes (n = 20,990) as additional covariates." (PMID 33682710, 2021). "Therefore, we evaluated the impact of known AD risk factors (APOE ε4, low education, hypertension, diabetes, dyslipidemia, and obesity) on cognitive trajectories in EOAD and LOAD patients." (PMID 34127075, 2021). "A total of 154 PD patients were assessed for vascular risk factors (hypertension, diabetes mellitus, and dyslipidemia), autonomic dysfunction (orthostatic hypotension and supine hypertension [SH]), APOE ε4 genotype, rapid eye movement sleep-behavior disorder, motor symptoms, and cognition status." (PMID 34376695, 2021). "Based on these exciting results, apoE mimetic peptides may be ideal candidates for the treatment of inflammatory complications associated with severe hypertriglyceridemia and diabetes." (PMID 33922449, 2021). "Moreover, apolipoprotein E polymorphism has been associated with higher risk of diabetes, and thus diabetic individuals tend to have lower serum levels of apolipoptorein E and impaired lipid transport." (PMID 32865658, 2021). "Other recognized risk factors include family history, degeneration or vascular dysfunction, obesity, hypotension or hypertension, diabetes, hyperlipidemia, low levels of education, physical inactivity, and the existence of epsilon 4 allele of the apolipoprotein E gene (ApoE4)." (PMID 32824404, 2020). "Contrary to the assumed dominance of hypertension as the biggest predictor of WMH burden, we show associations with a number of risk factors including diabetes, heavy smoking, APOE ε4/ε4 status and high waist-to-hip ratio of similar, or greater magnitude to hypertension." (PMID 32971464, 2020). "However, at the same time, diabetes was associated with the non-APOE genotype in an AD patient group." (PMID 30866553, 2019). "Diabetes along with the APOE ε4 allele might cause neuronal and vessel damage, increasing the risk for AD or mixed dementias." (PMID 30984391, 2019). "The APOE is an important gene that are associated with cardiovascular disease and diabetes." (PMID 31521122, 2019). "Similarly, Nox1 deficiency reduced plaque accumulation in ApoE−/− mice treated with streptozotocin, a drug that induces type 1 diabetes mellitus." (PMID 29710840, 2018). "Researches showed that APOE ε4 allele was associated with BMI, hypertension, and diabetes." (PMID 29074556, 2017). "In addition to diabetes, preliminary evidence in both in vitro and epidemio-logical settings suggest that ApoE ε4 is associated with a higher serum level of 25-hydroxyvitamin D." (PMID 27540764, 2016). "Besides the expected associations with serum lipid measures, we additionally observed that ApoE ε2 was associated with a higher risk of diabetes." (PMID 27540764, 2016). "Certain risk factors associated with AD, including diabetes mellitus, hyperinsulinemia and apolipoprotein E (APOE)-ε4 allele, may facilitate disease onset, at least partly, by affecting the activity of IDE." (PMID 25738734, 2015). "Contradictory results have been obtained with regards to the role of APOE variants in diabetes, which may be due to population-specific effects and variations in study designs." (PMID 26074879, 2015). "The interactions showed that the OR for the joint effects of an APOE ε4 allele or diabetes with high PP was lower than that for APOE ε4 or diabetes with low PP (i.e., APOE ε4 or diabetes alone), but comparable to the elevated estimates of OR in APOE ε4 allele non-carriers and in non-diabetics." (PMID 26441635, 2015).
diabetes (continued). "The distributions of the following variables were similar between ChEI non-responders and responders: age, sex, education level, cigarette smoking, alcohol consumption, vascular risk factors (hypertension and type 2 diabetes mellitus), APOE ε4 status, types of ChEIs, and drug-related side effects." (PMID 24391883, 2013). "The association of diabetes with cognitive function was investigated with multiple linear or, if appropriate, logistic regression analysis adjusting for other cardiovascular risk factors and APOE ε4 carriership." (PMID 24367577, 2013). "It is, however, unclear whether apoE gene polymorphism is also associated with increased risk of type 2 diabetes mellitus (T2DM)." (PMID 22520940, 2012). "Evidence for an up-regulation of EDHF-mediated relaxation is seen in small resistance arteries and arterioles from animal models of diet-induced obesity, hypercholesterolemia, hypertension, diabetes and in ApoE and LDL receptor-deficient mice fed a high fat diet in adult life." (PMID 23227196, 2012). "Thus, we reasoned that BALB.apoE-/- mice would be less susceptible to diabetes than B6.apoE-/- mice due to their higher HDL and low inflammation." (PMID 22204493, 2011). "A hypothetical explanation for these discrepancies might be associated with an earlier onset of AD, diabetes, and related complications in APOE ε4/ε4 persons, and, therefore, the lower likelihood of their participation in this cohort of community-dwelling adults." (PMID 40606939, 2025). "Additionally, the presence of the E4 allele in the APOE (apolipoprotein E) gene, occurring in 16% of the population, is considered the most important risk factor, followed by cerebrovascular diseases, diabetes, hypertension, head injuries, stress, and environmental factors." (PMID 40722590, 2025). "Clinically, APOE typing may identify high-risk patients who could benefit from intensified lipid control and neuroprotective interventions, aligning with the precision-medicine agenda in diabetes care." (PMID 41488146, 2025). "Possible reasons for the sex difference in CF might be variance in sex hormone reductions (androgens and estrogens), genetic risks (e.g., apolipoprotein E epsilon 4 allele), brain structure, volum, and glucose metabolism, and some diseases (e.g., diabetes and cardiovascular diseases)." (PMID 38287238, 2024). "Similarly, a synergistic effect of APOE ε4 and diabetes on the risk of AD was previously found, which, according to the authors, may be mediated by AGEs44." (PMID 38218902, 2024). "However, it is unclear whether ApoE is associated with PAD in Chinese type 2 diabetes mellitus (T2DM) patients." (PMID 32211081, 2020). "Whilst some evidence suggests that obesity may modulate the association between APOE genotype and fasting insulin and glucose levels, and hence potentially inflammation in men, other studies point to independent effects of obesity, diabetes, and APOE genotype to LOAD risk." (PMID 30735826, 2019). "This vascular model hypothesized that vascular risk factors such as hypertension and diabetes in conjunction with genetic factors like ε4 allele of apolipoprotein E (APOE ε4) cause vascular damage first in the presence of BBB disruption and mild hypoperfusion or oligemia (hit 1)." (PMID 29342116, 2018). "In addition to the impact on the serum lipid profile, blood pressure levels, the occurrence and development of type 2 diabetes mellitus and neurodegenerative disorders, polymorphisms of the APOE gene are also associated with the risk of cardiovascular diseases." (PMID 25356596, 2014).
diabetes (continued). "Finally, previous studies have suggested that the APOE ε4 allele may modify the associations of certain CRFs, e.g. smoking and diabetes, with cognitive impairment." (PMID 23741513, 2013). "Therefore, it is still unclear whether APOE ε4 carriership modifies the association of diabetes with cognitive dysfunction." (PMID 24367577, 2013). "It has also been shown that hypertriglyceridemia in patients with diabetes increases platelet activation through apolipoprotein E (ApoE)." (PMID 40362167, 2025). "Results revealed that exogenous aPC treatment prevented the diabetes-induced reduction in macrophages efferocytosis and that aPC’s effect was lost in diabetic ApoE−/− mice treated with MerTK specific morpholino." (PMID 41083981, 2025). "Studies on the Finnish population have proven that the prevalence of coronary artery disease (CAD) in diabetes patients varied according to types of APOE genotypes, which was 81% in E4 patients, 58% in E3/3 patients, and 53% in E2/2 or E2/3 patients." (PMID 40625502, 2025). "By using these datasets, we recently succeeded in analyzing the effects of APOE genotype, diabetes, and obesity on AD and vascular‐related pathological features." (PMID 39621511, 2025). "Several of the identified loci have been implicated in ASCVD risk factors such as circulating lipids (LPA-PLG, APOE, TRIB1, KANK2), diabetes (CDKN2B-AS1, IGF2BP1) and obesity (LEPR, IGF2BP1)." (PMID 40164586, 2025). "NHB Hispanic, and NHW participants prevalences were APOE ε4 (32.2%, 27.4%, 17.6%), diabetes (26.1%, 35.0%, 13.9%), hypertension (79.0%, 63.6%, 58.2%), obesity (56.8%, 50.3%, 38.5%), and tobacco dependence (12.9%, 7.5%, 3.9%)." (PMID 41035086, 2025). "Accuracy was lower in participants aged ≥80 years (83%), but was unaffected by chronic kidney disease, diabetes, sex, APOE genotype or cognitive stage." (PMID 40205199, 2025). "Like in our current cohort, the French study reported fewer APOE ε4 carriers in the diabetes group than in controls (24.6 vs. 30.6 %, p-value = 0.05)." (PMID 40606939, 2025). "IHD was associated with FW [β = 0.013 (0.001, 0.024), p = 0.032], after controlling for age, sex, education, right handedness, APOE ε4, hypertension, diabetes mellitus, hyperlipidemia, smoking, atrial fibrillation, and heart failure." (PMID 40015755, 2025). "This highlights the need for standardized protocols and larger, multi-ethnic cohorts to clearly determine the role of APOE in diabetes and related complications." (PMID 41488146, 2025). "Depression, anxiety and hypertension were also more common, while APOE ε4, ischaemic heart disease and diabetes showed little variation across tertiles." (PMID 41275373, 2025). "The hospitalization effects in the final CFM were adjusted firstly for age, sex and education, and then the selected covariates (NESB, years of diabetes, GDS score, smoking packyears, alcohol consumption and self‐reported general health and APOE*4 allele." (PMID 40312128, 2025). "The difference remained significant after adjusting for demographic and comorbidity characteristics including age, sex, BMI, education, APOE genotype, stroke, hypertension, and diabetes (P < 0.001)." (PMID 38347655, 2024). "Among Egyptian populations, APOE genotyping has been linked to coronary artery disease (CAD), coronary heart disease (CHD), type 2 diabetes mellitus (T2DM) with cardiovascular disease (CVD), T2DM with nephropathy (T2DMN), T2DM with obesity, and obesity." (PMID 39138505, 2024). "For the first time to the best of our knowledge, we provide evidence for cardiac dysfunction from diabetes in ApoE KO mice, occurring through inflammatory mechanisms and upregulation of necroptosis cell death." (PMID 38390337, 2024). "All models were adjusted for sex, age, ApoE status, socioeconomic status, anamnestic stroke, and diabetes." (PMID 39726764, 2024).
diabetes (continued). "These associations remained significant after adjustment for age, sex, low education, hypertension, diabetes, eGFR, BMI, history of stroke, smoking habits, sedentariness, and APOE‐ε4 (all P for trend <0.001), except in the case of plasma p‐τ181." (PMID 38606661, 2024). "Stronger effects were seen in apolipoprotein E (APOE) ε4 carriers (1.34 [0.98–1.82]) and in participants with diabetes (1.35 [0.94–1.94])." (PMID 38218902, 2024). "We constructed a diabetes mellitus (DM) + high-fat diet (HFD) mouse model based on the streptozotocin (STZ)-induced apolipoprotein E-knockdown (ApopE−/−) mouse to investigate the roles and regulatory mechanism of miR-449a/CEACAM1 axis." (PMID 38715117, 2024). "As such, in our ApoE KO mouse model, we found an upregulation of TNFα and IL-6 in dyslipidemic mice exacerbated by diabetes." (PMID 38390337, 2024). "In terms of cardiovascular health, APOE ε4 carriage was previously associated with CVD (IHD and myocardial infarction) and CVD risk factors (such as hypertension and diabetes)." (PMID 38509472, 2024). "STZ treated ApoE-/- mice developed diabetes, with significantly (p<0.05) increased blood glucose and body weight loss." (PMID 38390337, 2024). "Previous studies reported that APOE-ε4 carriers were more likely to develop insulin resistance and exhibited a stronger tendency to develop diabetes." (PMID 39020335, 2024). "Given that BMI was negatively associated with NFT and amyloid plaque counts in multiple brain regions, a partial correlation analysis adjusted for BMI in addition to sex, race, education, ApoE genotype, diabetes, and hypertension was also performed." (PMID 39199242, 2024). "The occurrence of diabetes in ApoE KO mice was confirmed by increased blood glucose levels and decreased body weights post STZ injection." (PMID 38390337, 2024). "Next, baseline levels of plasma Aβ were examined after adjustment for covariates (age, sex, APOE ε4 carrier status, years of education, cognitive status, fasting status, BMI, and status for hypertension, diabetes and stroke)." (PMID 38956096, 2024). "After adjusting for sex, race, education, ApoE genotype, diabetes, and hypertension, TC %RRR-αT was inversely correlated with DP counts in the FC (ρ = −0.35, p = 0.032) and TC (ρ = −0.34, p = 0.038)." (PMID 39199242, 2024). "None of the three CSF biomarkers showed a significant correlation with any macular VD measurements, adjusted by age, APOE ε4 status, hypertension, diabetes mellitus, dyslipidemia, heart disease, COPD, smoking habit and CSF technique (all r < 0.13; p ≥ 0.133)." (PMID 36908784, 2023). "CXCR7 agonism reduces atherosclerotic lesions in apolipoprotein E (ApoE−/−) mice fed a high fat diet and promotes endothelial repair in a diabetic limb ischemia model." (PMID 37945645, 2023). "After variable selection by LASSO Cox regression, CN Model 2 included age, SBP, ADAS11, RAVLT, LM-DR, FAQ, history of diabetes and history of depression, APOE ε4 status and hippocampus volume." (PMID 37904154, 2023). "Our study is the first to reveal ApoE genotypes related with lipids in patients with diabetes in an older Chinese community." (PMID 37123009, 2023). "In summary, we demonstrated the significant correlations of microbiome in older adults with their brain imaging markers, APOE genotypes, calcium intake, vegetable intakes, diabetes, and obesity." (PMID 37736325, 2023). "In our experimental setup, both the control and diabetic group are from the ApoE-KO mouse strain, where diabetes is induced by STZ injections (citrate only in the control group) followed by a cholesterol-enriched diet." (PMID 37069341, 2023).